TNF (tumor necrosis factor)
Diseases named in the same sentence as TNF in open-access papers (continued):
Sharing a sentence is not in itself a finding about the gene and the disease.
COVID-19 (continued). "Then, the cytokines (including CRP, Ferritin, IL-6, TNF-α, GM-CSF, IP-10, and MCP1α/1β) in the serum of severe patients with COVID-19 were higher than that in the mild patients with COVID-19, while the number of T and NK cells decreased and the number of neutrophils increased." (PMID 34667157, 2021). "Severe COVID-19 cases also revealed higher levels of IL-2, IL-6, IL-10, and TNFα." (PMID 33869282, 2021). "A double-blinded randomized controlled trial demonstrated that Xuebijing injection may suppress the cytokine storm and prevent the progression to ARDS in severe COVID-19 patients by regulating the secretion of pro-inflammatory cytokine IL-6, IL-8, and TNF-α." (PMID 34421581, 2021). "In addition, COVID-19 group showed increased TNF-α level and decreased IL-2, IL-6, IL-10, and IFN-γ levels." (PMID 34667157, 2021). "Analysis of plasma from patients with COVID-19 has revealed increases in cytokines, including IL-1β, IL-2, IL-6, IL-7, IL-10, TNFα, monocyte chemoattractant protein (MCP1/CCL2), granulocyte colony stimulating factor (G-CSF), and macrophage inflammatory protein 1α (MIP1α/CCL3)." (PMID 34251989, 2021). "In a recent study 1,484 patients with suspected or confirmed COVID-19 were investigated with a conclusion that the levels of IL-6 and TNF alpha in serum at presentation are predictive of COVID-19 survival and mortality, independently of demographics and comorbidities." (PMID 34149697, 2021). "However, the differences became significant by comparing COVID-19 symptomatic subgroup with controls (TNFα p = 0.005; GM-CSF p = 0.002), highlighting that more inflammation was detectable in the subjects undergoing a more severe course of the disease." (PMID 34248910, 2021). "Supporting this hypothesis, critical COVID-19 has been associated with high levels of interferon-γ (IFN-γ), tumor necrosis factor-α (TNF-α), numerous interleukins (ILs), macrophage inflammatory proteins (MIPs), and IFN γ-induced protein 10 (IP-10)." (PMID 35111777, 2021). "Three RCTs reported the effect of oral CHM as an adjuvant on TNF-α during COVID-19." (PMID 35127733, 2021). "Our data also suggested that the neutralization of TNF-α may be a therapeutic option to interrupt the vicious circle that links the viral infection to cytokine storm in COVID-19 patients with cardiac impairment." (PMID 34576032, 2021). "Moreover, CO2 treatment is the most effective method for inactivating ERK1/2 in epithelial cells in the presence of increased IFNγ and TNFα levels, which is characteristic of severe COVID-19." (PMID 34741187, 2021). "The consequences of these protein interactions need to be experimentally elucidated, however our results suggest that altered levels of TNF, IL-6 and CXCL9 in COPD patients may be involved in the initial steps that predispose COPD patients to severe COVID-19." (PMID 34335580, 2021). "Indeed, the clinical manifestation of COVID-19 is marked by higher concentrations of IL-2, IL-6, IL-8, TNFα, IFNγ, MCP1, MIP1α, IP-10, and GMCSF in patients’ blood." (PMID 34866574, 2021). "We next evaluated whether TNF-α, and IL-1β, two cytokines observed in COVID-19 patients, can decrease KLF2 gene expression." (PMID 34253708, 2021). "The phenomenon of synergistic killing by IFN-γ/TNF-α was first reported in cancer cells in 1983 and extends to multiple non-transformed cell types, including IECs and most recently macrophages in the context of COVID-19." (PMID 34556638, 2021). "It has been elucidated that the prognosis of COVID-19 could be worsened by the secretion of pro-inflammatory cytokines, including interleukins, IFNγ, and TNF-α." (PMID 34202374, 2021). "Here, it is essential to note that some research groups suggest that the baseline level of TNF is not distinct between mildly, severely, and critically ill patients with COVID-19, but others propose that the TNF level is higher in severely ill COVID-19 patients." (PMID 34445140, 2021).
COVID-19 (continued). "Second, frailty involving the process of complex chronic inflammation and proinflammatory cytokines, such as C-reactive protein, tumor necrosis factor (TNF)-a, interleukin (IL) or interleukin-6, exacerbates the risk of mortality when patients contract COVID-19." (PMID 33731018, 2021). "In terms of laboratory findings, an increased erythrocyte sedimentation rate (ESR) and elevated levels of C-reactive protein (CRP), lactate dehydrogenase (LDH), ferritin, interleukin 6 (IL-6), and tumor necrosis factor-α (TNF-α) are commonly observed in patients with COVID-19." (PMID 34295915, 2021). "In addition to the chemokines MCP-1/CCL2 and MIP-1α/CCL3, which were increased in COVID-19 patients, IL-6 and TNF-α production also depends on NF-κB activation." (PMID 33232303, 2021). "Subsequently, to further determine whether SARS-CoV-2 infection in AAV/hACE2 mice model could also induce proinflammatory mediators as shown in severe COVID-19 patients, RNA levels of TNF-α, IL-1β, IL-6, CCL2, and CXCL10 in mice lung homogenates were measured." (PMID 34379705, 2021). "In the initial release of data, there was no definite signal that anti-TNF use was associated with a higher risk of severe COVID-19." (PMID 34755038, 2021). "In addition, TNF were found to promote T cell apoptosis, which is possibly why TNF levels inversely correlate with T cell counts in COVID-19 patients requiring intensive care." (PMID 34943881, 2021). "Recent studies have found that the production of IL-1β, IL-18, TNF-α, and IL-6 was high in severe COVID-19 patients especially those with severe respiratory failure and are linked to the cytokine storm; these cytokines are downstream of the TLR4 canonical MyD88-dependent pathway." (PMID 33505220, 2021). "COVID-19 patients have higher circulating levels of TNF-α in the plasma and tissues." (PMID 34812049, 2021). "TNF-α is elevated in most COVID-19 patients and correlates with the severity of the disease." (PMID 34575258, 2021). "Moreover, an inverse relationship exists between TNF levels and total T-cell counts in COVID-19 patients." (PMID 33821263, 2021). "Our study identified that drug molecule andrographolide, naturally present in a medicinal plant Andrographis paniculata, has the potential to bind with crucial proteins to block the TNF-induced NFkB1 signaling pathway responsible for cytokine storm in COVID-19 patients." (PMID 34248936, 2021). "However, studies showed that these patients with COVID-19 present a high expression of tumor necrosis factor (TNF)-α, interleukin (IL)-1β, and IL-6." (PMID 33776796, 2021). "Moreover, IL-1β and TNF-α promote the response of Th17, by producing IL-17, although their role in COVID-19 immunopathogenesis is still to be clarified." (PMID 33669218, 2021). "First reports suggest that administration of MSCs is safe in patients with ARDS and may limit the cytokine storm (by reducing the levels of C-Reactive Protein, IL-6 or TNF-α) and improve oxygenation in severe COVID-19 patients." (PMID 34887773, 2021). "Most COVID-19 patients with ARDS are associated with elevated levels of various cytokines, including interleukin (IL)-2, IL-6, IL-7, interferon-γ inducible protein 10 (CXCL10), granulocyte colony-stimulating factor (G-CSF), and tumor necrosis factor-α (TNF-α)." (PMID 35401158, 2021). "In parallel, a recent report showed enhanced TREM2 protein levels in the CSF of a patient with COVID-19-associated encephalopathy, along with increased protein levels of IL6, IL8, and TNF in both CSF and serum (see section “Microglia Respond to the Systemic Inflammatory Response in COVID-19”)." (PMID 33737867, 2021). "Similarly, in our analyses, TNF-α signaling via NF-kB was found to be shared between COVID-19 and its comorbid conditions—cancers, CVDs, and CKDs." (PMID 34067609, 2021). "This information becomes more significant in patients with COVID-19, wherein increased levels of TNF-alpha and IL-6 may directly decrease albumin production and lead to hypoalbuminemia." (PMID 34683480, 2021).
COVID-19 (continued). "Another characteristic of severe COVID-19 patients is the cytokine storm: over-production of numerous cytokines and chemokines such as interleukin-6 (IL-6), tumor necrosis factor-α (TNF-α), monocyte chemotactic protein-1 (CCL2), and chemokine (C-X-C motif) ligand 10 (CXCL10)." (PMID 34764867, 2021). "In COVID-19 patients, the cytokine storm was mediated by high-levels of proinflammatory cytokines, and the severe cases showed significantly higher cytokines and chemokines, such as TNF-α, IL-6, and IL-10 expressed." (PMID 34439967, 2021). "Thus, both IFN-γ and TNF-α are pro-inflammatory cytokines highly upregulated in patients with COVID-19." (PMID 34224085, 2021). "In the milder stage of COVID-19, a positive correlation was detected between IL-33 and IL-1β, IL-12 and IL-23, while a stronger positive correlation between the serum values of IL-33 and TNF-α, IL-1β, IL-6, and IL-12 and IL-23 was detected in patients with COVID-19 with severe disease." (PMID 34917631, 2021). "Chloroquine inhibits the production and release of tumor necrosis factor (TNF) and interleukin-6 (IL-6), suggesting that it could suppress the cytokine storm in COVID-19 patients." (PMID 34099015, 2021). "Total T cells, and CD4+ and CD8+ T cell counts are negatively correlated with serum IL-6, IL-10, and TNF-α levels in COVID-19 patients, and patients in the disease resolution period exhibit decreased IL-6, IL-10, and TNF-α concentrations and restored T cell counts." (PMID 34818337, 2021). "For example, hyper-inflammatory responses including high levels of circulating cytokines and chemokines (particularly interleukin (IL)-6, IL-8, and tumor necrosis factor (TNF)-α), lymphopenia and immune cell infiltration in infected organs are considered major determinants of COVID-19 severity." (PMID 34320031, 2021). "A noticeable meta-analysis of the anti-inflammatory capacity of melatonin administration has recently confirmed, based on 13 studies and a global cohort of 749 people, the reduction of TNF-α and IL-6 levels, suggesting that it would have a similar effect on COVID-19 patients." (PMID 34356384, 2021). "Moreover, a significant correlation between COVID-19 severity and the serum concentrations of IL-1, IL-2, IL-6, IL-7, IL-10, TNF-α, G-CSF, CCL2, CCL3, CXCL8, and CXCL10 has been observed." (PMID 34209845, 2021). "In contrast to the severe COVID-19 group, the critical COVID-19 group was notable for the existence of more and different correlations between proinflammatory cytokines: TNF-α, IL-1β and cells, including lymphocyte subpopulations: T lymphocytes CD8+, B lymphocytes and Treg cells." (PMID 34064802, 2021). "In an older, sedentary population (61–66 years), 6 months of both AE and RE resulted in increased circulating levels of anti-inflammatory IL-10 and reduced levels of IL-6, CRP, and TNF-α, which are all involved in the cytokine storm observed in severe cases of COVID-19." (PMID 33001410, 2020). "An increase in proinflammatory cytokine, TNFα, has also been reported in BMVECs exposed to cocaine, which could be a concern for endothelial health in COVID-19." (PMID 32708495, 2020). "Emerging evidence indicates that there are potential benefits when managing the cytokine storm in COVID-19 patients by administering steroids, IL-6/IL-6-receptor (IL-6R) blocking antibodies, TNF inhibitors, IL-1 antagonists, and Janus kinase inhibitor (JAK) inhibitors." (PMID 33072097, 2020). "Vitamin D3 has a decisive role in the regulation of the innate and adaptive immune responses implying that adequate intake of vitamin D3 may protect patients with COVID-19 at least, in part by inhibiting the excess production of IL-6 and TNF-α." (PMID 33390994, 2020). "Anti-TNF drugs, including infliximab, adalimumab, etanercept, golimumab, and certolizumab, could be tested also for COVID-19-related ARDS and pneumonia." (PMID 32527304, 2020).
COVID-19 (continued). "Finally, we demonstrated the overproduction of tumor necrosis factor (TNF)-α in the lungs of all patients with COVID-19." (PMID 33424804, 2020). "Cytokine storm pathophysiology in CoViD-19 is often reported to be due to high levels of IL-6 in individuals, although this, we believe, could synergize with TNF-α and IL-1β levels." (PMID 32574269, 2020). "Studies have shown increased amounts of cytokines, such as IL-1β, IL-1ra, IL-6, TNF-α, IL-7, IL-8, IL-9, IL-10, FGF basic, G-CSF, GM-CSF, IFN-γ, IP-10, MCP-1, MIP-1a, MIP-1b, in the serum of COVID-19 patients, and the cytokine storm was associated with disease severity." (PMID 32426374, 2020). "The massive release of TNF-α, IFN-γ, IL-1β, IL-8, MCP-1, and IP-10 seen in acute phase of COVID-19 patients may probably be linked to pyroptosis, especially in lymphocytes through the NLRP3 inflammasome activation." (PMID 33193349, 2020). "Some authors had mentioned the use of TNF-α inhibitors for COVID-19 treatment." (PMID 33426096, 2020). "By comparing COVID-19 and severe influenza, we report that the TNF/IL-1β-driven inflammatory response was dominant in COVID-19 across all types of cells among PBMCs, whereas the up-regulation of various interferon-stimulated genes (ISGs) was prominent in severe influenza." (PMID 32651212, 2020). "NF-κB, IL-6, TNF are considered to be therapeutic targets for COVID-19." (PMID 33041797, 2020). "These preliminary findings support a role for the blockade of TNF-α in the treatment of the COVID-19 inflammatory cascade, with possibilities extending to the use of other TNF treatments ((Infliximab, Adalimumab, Golimumab)/Fab′-PEG (Certolizumab) Fusion TNFR2-IgG1-Fc (Etanercept))." (PMID 33426096, 2020). "Notably, TNF-α production was much higher in the liver of patient 1 and in the kidneys of all patients with COVID-19, as well as in the spleen of all patients with COVID-19." (PMID 33424804, 2020). "A range of strategies have been proposed and are being evaluated to dampen hyper-inflammation in COVID-19 such as corticosteroid therapies, antibodies against IL-1 or IL-6, treatments interfering with the interferon pathway and anti-tumor necrosis factor therapies." (PMID 32922409, 2020). "Interestingly, ACE2 shedding is enhanced not only by binding with spike protein, but also by IL-1β and TNFα inflammatory cytokines, cytokines that are secreted at relatively high concentration in COVID-19 patients." (PMID 32708755, 2020). "Gamma-linolenic acid, as a bioactive lipid, inhibits the production of pro-inflammatory IL-6 and TNF-α and could be employed to treat cytokine storm that is seen in COVID-19 patients." (PMID 33244381, 2020). "In addition, increased levels of plasma pro-inflammatory cytokines such as Interleukin (IL)-1β, IL-6, IL-8, and tumor necrosis factor-α (TNF-a) are observed in severe COVID-19 patients, indicative of a cytokine storm and subsequent ARDS development." (PMID 32695122, 2020). "• Significantly higher levels of IL-6, IL-8, and TNF-α were observed in serum of COVID-19 patients as compared to the healthy control or patients with multiple myeloma.• IL-6, IL-8, and TNF-α were associated with worst disease outcome and suggested as the predictive indicators of the disease." (PMID 33335518, 2020). "A case report study, treating a child with Crohn's disease and affected by COVID-19, used anti-TNF (Infliximab) with positive results, demonstrated by an improved cytokine profile, with normalization of TNF-α, and a decrease of IL-6 and IL-8 concentrations in blood." (PMID 33426096, 2020). "In two severe cases of COVID-19, lung injuries and cavities were filled with macrophages and neutrophils, where a fibrinous exudate could be detected, along with IL-6, TNF-α, and PD-L1 and a decrease in lymphocytes." (PMID 33324210, 2020). "COVID-19 immunopathology is characterized by the elevation of IL-6 and TNF-α." (PMID 34211530, 2020).
COVID-19 (continued). "In patients diagnosed with severe COVID-19, increased levels of pro-inflammatory cytokines, in particular the soluble interleukin 2 receptor (IL-2R), interleukin-6 (IL-6), and tumor necrosis factor-α (TNF-α), have been observed." (PMID 32546188, 2020). "As expected, higher plasma levels of pro-inflammatory cytokines IL1β, IL6, IL8, and TNFα at admission and before specific treatment were positively correlated with the severity of COVID-19 symptoms (p < 0.0001 for all cytokines), confirming the results from previous studies." (PMID 33585507, 2020). "Collectively, these findings suggested that IL-10 and TNF-α as immunosuppressive and pro-inflammatory agents, respectively,—might be prognostic and could serve as therapeutic targets for COVID-19." (PMID 33424804, 2020). "However, we observed a more unbalanced inflammatory/anti-inflammatory cytokine response in COVID-19 patients, as reflected by the IL-6:IL-10 and TNF-α:IL-10 ratios." (PMID 33272291, 2020). "Anti-TNFα agents used in autoimmune diseases, such as RA and ulcerative colitis, in principle, may have a role in treating severe respiratory syndrome of COVID-19." (PMID 32574268, 2020). "Additionally, the proportion of CD8+ T cells producing TNF-α was significantly higher in COVID-19 patients compared to healthy controls (p = 0.0214), and a similar tendency was observed for CD4+ T cells." (PMID 32707842, 2020). "Similarly, severe COVID-19 patients have higher concentrations of IL-2, IL-6, IL-8 and TNF in the serum than mild cases, suggesting that the magnitude of cytokine storm is associated with the severity of the disease." (PMID 32698440, 2020). "Furthermore, highly elevated serum IL-6, IL-8 and TNF-α in patients with COVID-19 are strong and independent predictors of COVID-19 severity and survival, which suggests the „cytokine storm“ indeed as crucial target for therapy." (PMID 33162939, 2020). "Moreover, we found a rise in TNF-α-secreting CD8+ T cells as well as a similar tendency in CD4+ T cells obtained from COVID-19 patients." (PMID 32707842, 2020). "NSAIDs also have been shown to have a direct suppressive effect on NK cell IFN-γ and TNF-α production which may be beneficial for late stage COVID-19 patients." (PMID 32655581, 2020). "Moreover IL-1β, IL-2, IL-5, IL-18, TNFα, and GM-CSF became detectable in all the samples following co-culture between resting PBMCs from COVID-19 patients and DPSCs." (PMID 33634100, 2020). "Subjects with COVID-19 show decreased or normal leucocytes and lymphocytopenia, as well as a systemic elevation of pyrogenic cytokines such as interleukin (IL)-6, IL-10, and tumor necrosis factor (TNF)-α." (PMID 33292313, 2020). "Furthermore, there is emerging evidence of the importance of pro-inflammatory cytokines interleukin-6 (IL-6) and tumour necrosis factor (TNF-alpha) as predictors of mortality in patients with COVID-19 and that IL-6 blockade appears to be beneficial." (PMID 32933530, 2020). "Another study showed a similar trend, with plasma concentrations of IL-2, IL-7, IL-17, IL-10, MCP-1, MIP-1A, IP10, and TNF-α being observed to be higher in COVID-19 patients undergoing treatment in intensive care units than in any other category of COVID-19 patients." (PMID 32984253, 2020). "Despite the pulmonary injury, the production of pro-inflammatory cytokines including IL-1β, IL-6, TNF-α, macrophage inflammatory protein 1-α, interferon gamma-induced protein-10, and monocyte chemoattractant protein-1 were significantly enhanced in COVID-19 patients." (PMID 33041827, 2020). "Taken together, we demonstrate that CXCL10 is an important cytokine secreted from infected airway epithelial cells, and that these cells are unlikely to be the source of classic pro-inflammatory cytokines such as IL-6 and TNFα reported to be elevated in the systemic circulation of COVID-19 patients." (PMID 33284849, 2020).